TLR9 (toll like receptor 9)
Diseases named in the same sentence as TLR9 in open-access papers (continued):
Sharing a sentence is not in itself a finding about the gene and the disease.
lupus (continued). "The involvement of IRAK-4 in TLR7 and TLR9 signaling, coupled with the observation that dual inhibition of TLR7 and TLR9 in lupus-prone mice results in amelioration of disease symptoms, indicates that IRAK-4 may be a suitable therapeutic target for systemic lupus erythematosus (SLE)." (PMID 19689377, 2009). "Actually, lupus NK cells present a strong basal activation level and seem to be exhausted, as shown by both the high CD69 expression in medium and the moderate response (not reaching significance) to the TLR9 agonist, respectively, suggesting that NK cells have been pre-activated in vivo." (PMID 34012432, 2021). "Although the exact mechanism for this is not yet known, it has been suggested that lower levels of TLR9 expression lead to defective T regulatory cell activation which contributes to the decrease in number and immunosuppressive function of these cells in the MRL model of murine lupus." (PMID 23227085, 2012).
viral infection (143 papers, 2009 to 2025). "The investigation of genetic variants such as the TLR4 and TLR9 polymorphisms is justified because these innate immune receptors play a critical role in the body’s first line of defense against viral infections, including HPV." (PMID 41374999, 2025). "Mitochondrial DNA released due to viral infection is detected by receptors (TLR-9, NOD-Like Receptor Thermal Protein Domain Associated Protein 3 (NLRP3), and cyclic GMP-AMP synthase (cGAS)) that typically identify viral or bacterial DNA." (PMID 39742024, 2024). "The TLR9 (rs5743836) SNP—which is mapped in the promoter region of the gene affecting its transcription—has been related to increased susceptibility to other viral infections, such as dengue." (PMID 35967300, 2022). "Despite the potential for downregulated TLR9 to be associated with viral infection, our findings were to the contrary, with higher expression observed in HPV+ lines and lower expression in HPV– lines." (PMID 29416610, 2018). "Previous studies have shown that TLR9 polymorphisms are associated with various viral infections, including HIV-1, HPV16, and HCMV." (PMID 27105145, 2016). "IL-10 is also implicated in the development of secondary bacterial infections following viral infections or trauma, conditions associated with TLR-9 activation." (PMID 26218271, 2015). "It is important to remark that the allele A of this polymorphism of TLR9 has been associated with the susceptibility and severity of parasitic and viral infections." (PMID 24053111, 2013). "It has been associated with the participation of both TLR2 and TLR9 as response to several human viruses infection, including herpes simplex viruses (types 1 and 2), cytomegalovirus, hepatitis C, Epstein-Barr, and varicella-zoster virus." (PMID 24174969, 2013). "TLR‐9 is associated with cellular defense against viral infections and is hypothesized to function similarly against COVID‐19; thus, TAM activation may downregulate important cytokine functions in the immune and inflammasome response." (PMID 40476695, 2025). "However, emerging evidence suggests that other factors, such as mitochondrial DNA leakage, can also trigger TLR9 signaling pathways in the context of viral infections caused by RNA viruses, such as the flavivirus DENV and SARS-CoV-2." (PMID 39599884, 2024). "Genetic mutation in TLR4/TLR9 may alter the expression or function of encoded proteins and their association with susceptibility to viral infections has been reported in different populations." (PMID 36915050, 2023). "In chronic viral infections, a sustained stimulation of innate immunity may result in excessive and chronic activation of the toll-like receptors 9 (TLR9), which was shown to be linked to HLH/MAS-like syndrome in mouse models." (PMID 37065291, 2023). "Any genetic (single nucleotide polymorphisms, SNPs) or expression variation in TLR9 gene may modify the ability of the receptor to respond correctly to viral infection as in NPC." (PMID 31886298, 2019). "This deficiency may be further compounded by the TLR9-inhibiting effects of the E7 oncogene, once viral infection in established." (PMID 29416610, 2018). "In summary, targeting the ion channel sensor Piezo1 in neutrophils alters NET DNA production and TLR9 and cGAS signalling activities, thereby contributing to the reciprocal differentiation of M1 and M2 macrophages while responding to viral infection." (PMID 39890818, 2025). "Meanwhile, the protein levels of upstream TLR4 (bacterial infection response), TLR9 (viral infection response) and downstream iNOS were also inhibited synchronously." (PMID 39911394, 2025). "Prior to viral infection, TLR9 is expressed in the endoplasmic reticulum, upon infection, it is translocated into endosomes, where it binds CpG-containing viral DNA and signals through MyD88 to activate antiviral inflammatory pathways." (PMID 40791597, 2025).
viral infection (continued). "Nevertheless, detailed molecular mechanisms by which TLR9 affects B cell activation and differentiation during viral infection need further exploration." (PMID 40366175, 2025). "The heatmap showed upregulation of these inflammatory genes at different time points after viral infection when compared with those uninfected cells, and almost all of the inflammatory genes except Tlr9 showed significantly elevated transcription at 48 hpi." (PMID 38992966, 2025). "Previous studies had supported that TLR-9 expression was correlated to microbial and viral infections." (PMID 40076895, 2025). "The association of TLR7, TLR9, and Band 3 on the RBC surface during viral infection suggests a potential immune receptor complex on the RBC." (PMID 38982195, 2024). "TLR7 and TLR9, whose ligands are ssRNA and dsDNA, respectively, work as innate sensors for detecting viral infections." (PMID 36875095, 2023). "The TLR9-related immune system plays a crucial role in developing vaccines against viral infectious diseases." (PMID 38116008, 2023). "TLR7 and TLR9 pathway activation is also required for effective responses to vaccines and viral infections, such as COVID-19, which disproportionately affects Black individuals and Hispanics in both frequency and severity." (PMID 37606045, 2023). "Essentially, these studies provide the basis for a multidisciplinary exploration of TLR-9 convergence, immune responses, and viral infection in GC." (PMID 37894471, 2023). "EBV genetic material modulates TLR-9 expression patterns, suggesting a potential link between viral infection and immune system activation." (PMID 37894471, 2023). "During viral infection, TLR9 and STING activated the NF-κB signaling pathway, which attenuated the expression of NLRC3." (PMID 36341336, 2022). "This pro-inflammatory cytokine pattern is similar to that resulted after the viral infection or TLR-9 stimulation, suggesting a crosstalk between that innate and adaptive immunity influencing the antigen specific immune response." (PMID 35935966, 2022). "FAS is related to apoptosis pathway, and TLR9 is related to virus infection, both of them are involved in pathogenesis of EBV,24, 25 we chose FAS and TLR9 for further study." (PMID 33434416, 2021). "In contrast to this study, we chose early time points after TLR9 activation with CpG (2 h, 6 h, 12 h), which represent immediate events after virus infection during which pDCs rapidly produce type I IFN to fight infection." (PMID 34544361, 2021). "It was found that chronic viral infections can impair TLR9 signaling and down-regulate TLR9 gene expression." (PMID 34572011, 2021). "TLR3, TLR7, TLR8, and TLR9, which recognize double-stranded RNA (dsRNA) (TLR3), single-stranded RNA (ssRNA) (TLR7/8), and CpG DNA (TLR9), are mainly involved in viral infections." (PMID 33123162, 2020). "Among the TLR family, TLR3, TLR7, TLR8 and TLR9 are predominantly localized in intracellular compartments and form the key gatekeepers in detecting and combating viral infections." (PMID 33519463, 2020). "Viral infections or agonists of TLR7 or TLR9 can activate IRF5 in DCs in vitro in a MyD88-dependent manner." (PMID 31999809, 2020). "pDCs are well known for their capacity to secrete high levels of IFNα after TLR9 stimulation during viral infections." (PMID 33318509, 2020). "The upregulation of TLR9 following H1N1 infection suggested the potential for cross-talk between viral infection and bacterial genome sensing." (PMID 30682165, 2019). "SLC15A4, selectively transcribed in bovine and also in human pDC, was shown to be required for signaling through TLR7 and TLR9 in murine pDC and, as a consequence, for pDC-mediated control of persistent viral infection." (PMID 30425716, 2018). "They express high levels of type I interferons upon stimulation with agonists that mimic viral infection, such as ligands of Toll-like receptor 9 (TLR9)." (PMID 29301941, 2018).
viral infection (continued). "It is interesting to note that in all three species, TLR7 and TLR9 expression dominates in B cells, indicating an important role in sensing viral infections." (PMID 28890720, 2017). "NETs activate plasmacytoid dendritic cells through TLR9 during viral infections and autoimmune diseases and can mediate the priming of T cells, which requires NET–T cell contacts and T-cell receptor signaling." (PMID 28303140, 2017). "Unmethylated CpG induceda strong immune response in B cells and pDCsthrough TLR9 during viral infections." (PMID 25685743, 2015). "Taken together with the detection of RNA:DNA hybrids in endosomal fractions during a viral infection, these experiments also support the notion that endosomal sensing of RNA:DNA hybrids by TLR9 is physiologically relevant." (PMID 24514026, 2014). "pDCs typically respond to viral infection via endolysosome-localized TLR7- or TLR9 sensors that recognize RNA or DNA viral genomes, respectively." (PMID 25340500, 2014). "The contribution of these viral infections to low tumor TLR9 status in TNBC should therefore be addressed in future studies." (PMID 25101078, 2014). "Human TLR9 is only found on pDCs and recognizes viral DNA within the early endosomes at the initial phase of viral infection." (PMID 24174969, 2013). "Normal pDCs are known for their ability to quickly produce large amounts of IFN-α in response to viral infection or TLR9 ligation." (PMID 23141740, 2013). "During the pathogenesis of MS, TLR9 is able to recognize DNA within the early endosomes at the initial phase of viral infection." (PMID 24174969, 2013). "pDCs also express high levels of TLR7 and TLR9 to sense viral infections and mount type 1 interferon responses." (PMID 23055830, 2012). "TLR9 is also the major sensing mechanism for DNA viruses and TLR9 dependent recognition of virus infection results in production of Type I IFN." (PMID 21994776, 2011). "As expected, TLR-9-/- mice had a defect in the production of interferon (IFN)-β after viral infection." (PMID 21810214, 2011). "On histopathological examination, areas of alveolar fibrosis and consolidation were found to be increased in TLR-9-/- compared with Balb/c mice after fibrotic challenge and viral infection." (PMID 21810214, 2011). "Next, we evaluated whether TLR9 gets tyrosine phosphorylated during virus infection and used HSV-1 infection model." (PMID 40980882, 2025). "Interestingly, after virus infection in mice, Piezo1−/− mice presented reduced TLR9, cGAS, STING and IRF3 expression in macrophages in the BALF." (PMID 39890818, 2025). "Similar to the case of virus infection, pDCs may contribute to TLR9-mediated inflammation in autoimmune diseases, whereas cDCs mainly contribute to cGAS-mediated inflammation." (PMID 39254994, 2024). "Rapidly responding, germinal center–independent Tbet+ B cells were tracked to the splenic marginal zone during viral infections, and a TLR9/IFN-γ–dependent expansion of Tbet+ B cells in the marginal zone of spleens was observed in a rodent model of malaria reinfection." (PMID 38652559, 2024). "Additionally, TLR9 has been shown to be important in inducing the production of type I interferons (IFNs), particularly via plasmacytoid dendritic cells, during viral infection." (PMID 36992483, 2023). "Using CpG as an optimal TLR9 agonist and focusing on early events after virus infection, we found that after pDC activation more of the pDC chromatin landscape is "turned on" rather than "turned off“, both globally in the genome and also among the regions associated with TF genes themselves." (PMID 34544361, 2021). "Furthermore, pDCs limit viral disease through direct TLR9-mediated IFN-α secretion and by preventing Treg re-programming to effector ex-Tregs." (PMID 32877681, 2020). "Although only viral infection has been suspected as the cause of the IFN signature in SS, among the pattern recognition receptors mediating type I and III IFN induction, TLR4 and TLR9 can recognize bacterial components." (PMID 32208441, 2020).
viral infection (continued). "In addition, it has been shown that TLR9 contributes to the production of type I IFNs to systemic viral infections, while cytosolic nucleic acid sensors including cGAS, IFI16 (mouse: Ifi204), RIG-I, and MDA5 mediate local immune responses to viral infections." (PMID 29963044, 2018). "In addition, several reports have confirmed that chronic viral infections can impair TLR9 signaling and down-regulate TLR9 gene expression." (PMID 29026137, 2017). "Previous studies have shown that chronic viral infections can overcome and impair TLR9 pathway." (PMID 29026137, 2017). "TLR9, localized intracellularly within endolysosomes, recognizes unmethylated CpG dinucleotide motifs located in viral DNA and plays a central role in host defense against viral infection." (PMID 27105145, 2016). "In normal circumstances, TLR9 combines with unmethylated CpG motifs of the pathogen during bacterial or viral infection, thus stimulating the maturation and activation of dendritic cells and B cells and the elimination of pathogens by the secretion of cytokines and specific antibodies." (PMID 25780451, 2015). "Among these, TLR9 has gained special interest in viral diseases." (PMID 25133733, 2014). "In the case of the MCF7 cell line response to Ad-null viral infection, it is likely that an additional immune response is generated unrelated to splicing; e.g., a TLR9 response could account for this." (PMID 24650050, 2014). "To determine if the increased susceptibility to viral infection of the IL-21R KO mice could be due to an inherent altered expression of PRRs we measured mRNA levels of TLR2, TLR3, TLR9, MDA-5, AIM-2, DAI, RIG-I and IFI16." (PMID 24358128, 2013). "Indeed, pDCs represent an essential immune cell type for the initiation of both innate and adaptive immune responses to viral infections, and TLR9 is important for MCMV-mediated type I IFN production by pDCs." (PMID 23028824, 2012). "There are many potential mechanisms by which TLR-9 signaling might influence the fibrotic environment during viral infection." (PMID 21810214, 2011). "The TLR-9 responds to viral infections by producing type I IFN." (PMID 22114589, 2011). "As IFN-β is known to be a potent inhibitor of lung fibroblast proliferation, a fact we have confirmed, it is reasonable to conclude that early viral infection of fibroblasts would result in the stimulation of TLR-9 by viral CpG DNA sequences and a concomitant decrease in fibroblast proliferation." (PMID 21810214, 2011). "However, the TLR-9-/- mice had a greater increase in collagen on day 21 after viral infection than did wild-type mice (705.4 ± 52.8 versus 468.6 ± 42.2 μg/ml; P < 0.01; n = 5)." (PMID 21810214, 2011). "Recent data have shown that TLR-9 is upregulated in IPF; thus it is likely that viral infections via activation of TLR-9 could have a key role in the pathogenesis of IPF as well as in the acute exacerbation of the disease observed after an infection." (PMID 20937083, 2010). "Several hypotheses have been proposed for TLR9 activation during COVID-19, including mitochondrial dysfunction, which is an indirect mechanism related to various health issues and has been observed in different viral infections." (PMID 41011507, 2025). "Moreover, since TLR9 can be activated by the viral DNA as well as the mtDNA, viral infection may also induce uncontrolled endocytosis of AMPA receptors." (PMID 38354781, 2024). "Additionally, viral infections have long been considered to be highly associated with SS and may be related to human cytomegalovirus (HCMV)-induced stimulation of TLR7 and TLR9." (PMID 36248435, 2022). "Therefore, we speculate that the genetic variation of TLR9 that downregulates TLR9 expression could reduce the function of the innate immune response against viral infection." (PMID 34572011, 2021). "Furthermore, at the late stage of viral infections, Tlr9 may contribute to the production of type I IFNs in a systemic ECTV infection." (PMID 29963044, 2018).